HIF1A (hypoxia inducible factor 1 subunit alpha)
Diseases named in the same sentence as HIF1A in open-access papers (continued):
Sharing a sentence is not in itself a finding about the gene and the disease.
tumor (continued). "Nevertheless, ERK activation by PDGFRβ signaling pathway cannot compensate the loss of HIF1α-PDGFD-PDGFRα-AKT network for GBM tumor growth because knockout of either HIF1A or PDGFD or PDGFRA in U251 cells eradicated the tumor growth." (PMID 34470658, 2021). "In mamma carcinomas, HIF-1α-positivity is associated with higher proliferation rates and tumor size, higher grading status, shorter metastasis-free intervals, and negative hormone receptor status." (PMID 34671319, 2021). "Here, we synthesized melatonin‐like molecules with enhanced HIF‐1α targeting activity and less toxicity and investigated their effects on tumor growth and angiogenesis, as well as the underlying molecular mechanisms." (PMID 33955074, 2021). "Analysis of genetic screen data reveals that, in normoxia, HIF1A behaves as a strong tumor suppressor, which is genetically linked to its target DDIT4, a repressor of mTOR signaling." (PMID 33654095, 2021). "The tumor suppressor WWOX has been implicated in glucose homeostasis through regulating HIF1α and its target genes." (PMID 33520443, 2021). "Silencing HIF-1α in association with irradiation thus constitutes a promising strategy to target radioresistant tumor cells in hypoxic niches." (PMID 34359734, 2021). "HIF-1α is known to be involved in tumor progression and is mostly associated with poor patient’s outcome." (PMID 34572746, 2021). "Mice with macrophages containing only HIF-2α (HIF-1α-deficient) had a reduced number of TEMs, better vascular architecture, and increased oxygen that enabled better perfusion and enhanced tumor cytotoxicity." (PMID 35008355, 2021). "Fluorescence staining showed that HIF-1α expression was decreased, suggesting that the accumulation of MnO2 in the tumor caused the decomposition of H2O2 into O2 and alleviated the hypoxia of the tumor." (PMID 34039370, 2021). "With regard to HCC, BHLHE40 was shown to be activated by HIF-1α, suggesting its role in adaptation to a hypoxic microenvironment associated with tumor progression." (PMID 34045534, 2021). "Overexpression of HIF-1α causes tumor cells to release chemoattractants and chemokines that can recruit MDSCs to hypoxic regions." (PMID 33889304, 2021). "One of the strategies for overcoming this vicious circle associated with tumor blood vessels’ formation is the inhibition of HIF-1α." (PMID 34439079, 2021). "A small molecule, PX-478, has shown potent antitumor activity in mouse models, that seems to be associated with HIF-1α levels within the tumor." (PMID 34830491, 2021). "This study revealed a new mechanism underlying the tumor suppression ability of HIF1α and provides insights into the role of hypoxia and lipid metabolism in tumor progression." (PMID 34098990, 2021). "It thereby acts as a protein kinase and interacts with many tumor-associated genes to accelerate carcinogenesis including HIF1α, Oct-4, STAT3 and CTNNB1 that encode β-catenin." (PMID 33652661, 2021). "The loss of pericytes, reducing vessel coverage and stability, induces an impairment of the tumor blood flow that is associated with the emergence of tumor hypoxia and increased expression of HIF-1α." (PMID 34885027, 2021). "HIF-1α also mediates the susceptibility of tumor cells to CTL-mediated lysis by the upregulation of miR-210." (PMID 33422072, 2021). "Loss of VHL in OC stabilizes HIF-1α which in turn stimulates miR-210 expression inducing tumor aggressiveness." (PMID 35145899, 2021). "CRLX101 can suppress tumor hypoxia and HIF1α expression, thus counteracting undesirable effects caused by bevacizumab." (PMID 34948368, 2021). "Lactic acid induces expression of VEGF, Arg1 and other M2 genes in TAMs via HIF-1α stabilization, and this is critical for tumor growth, as Arg1-deficient macrophages impair tumor progression in vivo in a mouse model." (PMID 34079545, 2021). "TAM-associated HIF1α was significantly associated with high tumor grade and increased metastasis and was independently associated with decreased overall survival." (PMID 34384473, 2021).
tumor (continued). "In OSCC cells, reduced E-cadherin was associated with HIF expression, which is congruent with the finding that lymph node metastasis and tumour recurrence in OSCC patients was associated with HIF-1α and VEGF." (PMID 34094895, 2021). "Exercise increases the release of muscle-derived cytokines and increases the ligands associated with tyrosine kinase receptor attachment to the tumor and endothelial cells to stabilize HIF-1α expression, which occurs due to adaptation to exercise." (PMID 35083006, 2021). "The hypoxia-inducible factor-1α (HIF-1α) is one crucial facilitator for energy adaption and oxygen metabolic stress in hypoxia and nutrition deficiency tumor environment, and functions as a general regulator of tumor aggressiveness and metastasis as well." (PMID 34465721, 2021). "The up-regulated HIF-1α has been shown to facilitate immunosuppression and immune escape by modulating lymphocytes, myeloid-derived suppressive cells, dendritic cells, and tumor-associated macrophages." (PMID 33535466, 2021). "HIF1α, NFκB, and loss of Cav-1 have been implicated in the signaling that drives autophagy and catabolism in CAFs that can directly affect tumor growth." (PMID 34376225, 2021). "As a negative regulator of the Warburg effect, AMPK inhibits tumor growth by regulating glycolysis and lipogenesis of tumor cells through regulating HIF‐1α, while the loss of AMPK can promote tumorigenesis by regulating lipid metabolism." (PMID 34387383, 2021). "Higher LVD has been also found to be associated with overexpression of VEGF-C, VEGF-D, and HIF-1α, markers of local aggressiveness of the tumor." (PMID 33706734, 2021). "In a study of pancreatic cancer, tumor cells deficient in HIF-1α had glycogen accumulation and inflammatory cytokines secretion, which recruited cDC into tumor stroma." (PMID 33732237, 2021). "STAT3/HIF-1a axis plays a crucial role in adapting tumor cells to the hypoxic environment associated with cancer progression." (PMID 33672756, 2021). "We further evaluated the association between HIF1A levels and these immune cells before and after tumor recurrence." (PMID 34305618, 2021). "Mounting evidence has indicated the association between HIF-1α and the NF-κB signaling pathway in tumor cells." (PMID 34073155, 2021). "Hypoxia is a hallmark of the tumor microenvironment which induces hypoxia-inducible factor-1α (HIF-1α) for transcriptional regulation." (PMID 35008634, 2021). "They further associated SIRT1 with HIF-1α in the hypoxia-exposed tissues of mice that negatively regulated angiogenesis and tumor growth." (PMID 34803727, 2021). "FoxP3 is an important marker for Treg cells, and the expression of FoxP3+Treg is associated with the immune escape of tumor cells, while HIF‐1α can upregulate molecules that attract FoxP3+Treg." (PMID 34387383, 2021). "In the last decade, our group reported that several downstream factors regulated by HIF-1α were closely associated with tumor proliferation, angiogenesis, and the epithelial-mesenchymal transition." (PMID 33830713, 2021). "HIF-2α expression has been associated with necrotic regions, whereas HIF-1α expression has been diffusely distributed within the tumor nests." (PMID 34958428, 2021). "The importance of STAT3 activation was emphasized by Pawlus and his colleagues in a previous report, where STAT3 knockdown in tumor cells caused inhibition of proliferation, mimicking the phenotype displayed by NK cells after HIF-1α knockdown under hypoxia." (PMID 33920906, 2021). "Hypoxia of solid tumors and the resulting production/secretion of hypoxia-inducible factor-1alpha (HIF-1a) cause the up-regulation of PDL-1 expression in tumor-infiltrating myeloid cells (in particular in myeloid-derived suppressor cells, MDSCs)." (PMID 33429973, 2021).
tumor (continued). "Hypoxia-inducible factor-1α (HIF-1α), a key mediator in tumor metastasis and angiogenesis, is associated with poor patient prognosis and has been recognized as an important cancer drug target." (PMID 34194533, 2021). "Tumor-induced mutations in the binding pocket of pVHL have been shown to disrupt HIF-1α interactions and thereby disassemble the E3 ubiquitin ligase (VEC) complex." (PMID 34503254, 2021). "Acute and chronic hypoxia are mainly mediated by HIF1α and HIF2α, respectively, and have often been reported to be associated with tumor progression and aggressive phenotype." (PMID 33472628, 2021). "An increased expression of HIF-1α has been reported in a number of cancer cell lines, associated with tumor growth, metastasis, poor clinical prognosis, and chemoresistance." (PMID 33919449, 2021). "In clinical samples of endometrial, colorectal, thyroid, papillary cell renal cell carcinomas, and breast cancer, high tumor ascorbate levels were associated with low HIF-1α protein levels and low HIF target gene expression." (PMID 33842321, 2021). "CBP/p300 bind specifically to HIF-1α and are critical co-activators for HIF-1α-mediated gene expression under hypoxia conditions, which underlies tumor angiogenesis, invasion, metastasis, and resistance to therapy." (PMID 34201346, 2021). "Another factor important for vasculogenesis is matrix metalloproteinase-9 (MMP9), a downstream factor of HIF1α produced by recruited myeloid cells and tumor-associated inflammatory and stroma cells." (PMID 33921099, 2021). "These include tumor-associated macrophages (TAMs) and myeloid-derived suppressor cells (MDSCs), since it has been shown that hypoxia and HIF-1α drive their recruitment to the TME, as well as M2-like polarization and activity." (PMID 33806300, 2021). "The upregulation and activation of MMP‐2 in association with HIF‐1α expression enhance tumour cell infiltration and blood‐brain barrier permeability." (PMID 33300633, 2021). "Oxygen acts as a radiosensitizer, but vascular damage caused by radiation can exacerbate tumor hypoxia and lead to HIF-1α dependent consequences." (PMID 35127525, 2021). "SIRT1, a direct downstream target of HIF-1α, is a critical regulator of endothelial cell behavior and has been linked to tumor angiogenesis under hypoxic conditions." (PMID 34381712, 2021). "Of these, high expression of hypoxia-inducible factor 1 α (HIF1α) emerged as an novel hallmark pathway, which was described to be correlated with a hypoxic tumor microenvironment in ES." (PMID 34359637, 2021). "Hypoxia-inducible factor-1α (HIF-1α), a dominant regulator of a tumor cell's response to hypoxia, is closely associated with the progression and metastasis of several types of cancer, including PDAC." (PMID 34036383, 2021). "More importantly, the authors identified upregulation of MASPIN/SERPINB5, a tumor suppressor gene for UM, as well as downregulation of proteins related to angiogenesis, such as HIF-1α and VEGF, as cause of AEZS-108 efficacy." (PMID 33964953, 2021). "MiR-148a downregulates VEGF via the pERK/HIF-1α pathway, inhibits tumour angiogenesis and reduces the risk of early recurrence in CRC patients." (PMID 33865381, 2021). "Hypoxia-inducible factor-1α (HIF-1α) is activated in the hypoxic tumor microenvironment and promotes the transcription of genes associated with tumor invasion, proliferation and radio-resistance." (PMID 34917504, 2021). "Mutations of SDH lead to the stabilization of HIF-1α and, consequently, hypermethylation of DNA and histones, related to tumor progression." (PMID 34200820, 2021). "HIF-1α was also reported to be involved in the regulation of tumor progression-associated properties." (PMID 33964953, 2021). "Regarding the subgroup analysis by tumour type, the HIF-1α G1790A polymorphism was substantially related to a higher risk of OC in the five genetic models." (PMID 34256803, 2021).
tumor (continued). "miR-487a targeted the 3’-UTR of HIF-1α to induce the Warburg effect, which is a distinctive cellular metabolic mechanism in cancer cells that causes long-term tumor cell survival." (PMID 34162394, 2021). "A hypoxic tumor microenvironment favors up-regulation of CXCR4 and CXCL12 in monocytes, monocyte-derived macrophages, tumor-associated macrophages, endothelial cells, and cancer cells through a global regulator hypoxia-inducible factor-1 alpha (HIF-1α)." (PMID 34298991, 2021). "A cytoplasmic staining pattern for HIF-1α has also been documented in other tumor types, where it seems to be associated with more differentiated epithelial carcinoma cells." (PMID 33889304, 2021). "For example, lactic acid from glycolytic tumor cells can trigger HIF-1α-dependent polarization of tumor-associated macrophages." (PMID 33927894, 2021). "Nevertheless, it was also reported that HIF-1α suppresses tumor cell proliferation in VHL-deficient renal cell carcinoma through the repressed aspartate-producing enzymes GOT1 and GOT2 and thus impaired oxidative and reductive aspartate biogenesis." (PMID 34858835, 2021). "The increased HIF-1α expression has been found in numerous cancer cells and clinically linked with tumour growth, metastasis and poor clinical prognosis." (PMID 33673181, 2021). "Its expression is induced by HIF-1α and it is believed to regulate the expression and function of tumor-associated genes." (PMID 33673417, 2021). "HIF1α promotes Treg cells recruitment to the tumor sites and also promotes immune suppressive activity of MDSCs and tumor-associated macrophages (TAM)." (PMID 34068008, 2021). "PCRs specific for the recombined Hif1a and Hif2a alleles revealed that tumour DNA exhibited Cre-induced recombined alleles of these genes in tumours from the relevant mice." (PMID 32807776, 2020). "Arsenic accumulation in tumor tissues was observed to cause down-regulation of ROS levels and a significant reduction in hypoxia-inducible factors-1α (HIF-1α) expression, leading to the inhibition of NLRP3 expression." (PMID 33014808, 2020). "We found that AAE6 elevated the levels of glycolytic enzymes related to the tumour cell hallmark Warburg effect and that of hypoxia inducible factor 1 alpha (HIF-1α), possibly contributing to AAE6′s enhanced proliferative abilities." (PMID 33121134, 2020). "In fact, hypoxia can also decrease the expression of cell surface MHC class I-related chain molecules A (MICA) and prevents the immune cells degrading the tumor cell via a HIF-1α-dependent pathway linked to increased expression of metalloproteinase (MMP)." (PMID 32878021, 2020). "Tumor hypoxic microenvironment causes hypoxia inducible factor 1 alpha (HIF-1α) activation and necrosis with alarmins release." (PMID 32290386, 2020). "More specifically, CKD-516 + IR (d1) caused the most extensive tumor necrosis, which resulted in a significantly large hypoxic area (p = 0.02) and decreased HIF-1α, Glut-1, VEGF, and Ki-67 expression." (PMID 33143663, 2020). "The cascade of molecular events triggered by HIF-1α activation involves the secretion of cytokine and chemokines that attract monocytes, allowing for the differentiation into macrophages or tumor-associated macrophages (TAMs)." (PMID 32751958, 2020). "Increasing evidence has demonstrated that HIF-1α promoted the progression of EC through various mechanisms and was significantly associated with the tumor grade, lymph node metastasis, and tumor resistance to chemotherapy." (PMID 33110923, 2020). "Fumaric acid has been linked to the inhibition HIF-1α degradation in tumor cells to overcome hypoxia in multiple cancer types." (PMID 32156060, 2020).
tumor (continued). "In particular, upregulation of HIF-1α has been heavily implicated in cancer biology and is shown to affect varying aspects of the anti-tumor immune response, including the differentiation and function of immune cells within the TME." (PMID 32316260, 2020). "To assess the relative contributions of HIF1A to growth in the brain microenvironment versus in the mammary gland, we sought to determine the relative effects of HIF1A loss on tumor growth at either site." (PMID 33298946, 2020). "Hif-1α regulates the polarization of M1 and tumor-associated macrophages, both of which are under energetically challenged conditions." (PMID 32396064, 2020). "Knockdown of GPC3 expression was associated with tumor growth suppression, which was significantly reversed forcing the expression of HIF-1α." (PMID 32585931, 2020). "We previously revealed that intratumoral hypoxia caused by the rapid proliferation of tumor cells activates EMT through the directional regulation of Twist1 by hypoxia inducible factor-1α (HIF-1α)." (PMID 32509584, 2020). "Since G-6-P serves as a substrate for the PPP responsible for the biogenesis of the antioxidants NADPH and glutathione, the HIF-1α–mediated Warburg effect has been associated with the increased antioxidant capacity of tumor cells and eventual radioresistance." (PMID 32631383, 2020). "While HIF2A gain tumours exhibited very few alterations in immune scores, HIF1A loss tumours showed statistically significant increases or decreases in 57 of 83 immune signatures of a variety of lymphoid and myeloid lineage cells." (PMID 32807776, 2020). "Previous reports demonstrated that the accumulation of 18F-FDG within tumor cells was significantly linked to the presence of glucose transporter 1 (Glut1), hypoxia-inducible factor 1α (HIF-1α), and vascular endothelial growth factor (VEGF)b." (PMID 32156047, 2020). "It is imperative to say that HIF-1a signaling is stimulated not only by lowered oxygen tension but also by oncogenic stimulation through aberrant growth factors or the loss of tumor suppressors." (PMID 32493394, 2020). "High amounts of lactic acid present in the tumor microenvironment also stabilise the expression of HIF‐1α and cause M1 to M2 polarisation." (PMID 33363732, 2020). "The results show that alpinetin reduced ROS production, resulting in reduced ROS/NF‐Κb/HIF‐1α pathway activity, which leads to impaired cell proliferation and induction of mitochondria‐associated apoptosis, culminating in reduced tumour growth." (PMID 32562470, 2020). "This MRI parameter was mostly studied in adult cancers and in brain tumors, where, on ADC maps, the decrease of ADC mean values was significantly linked to tumor hypoxia and HIF-1α hyperexpression at diagnosis." (PMID 33092063, 2020). "Experiments performed with DMOG demonstrated that the inhibition of PHDs directly control the expression of Sdc-3, and we confirmed this finding with a HIF-1α deficient tumor cell line, and by the identification of several HREs on the Sdc-3 promoter." (PMID 33117401, 2020). "The over-expression of the PPP enzymes associated with HIF-1α stabilization and tumor progression has been reported as serving as an indicator of poor prognosis in cancer." (PMID 32252351, 2020). "EV-lncRNA-HISLA from tumor-associated macrophages, a protumoral polarized cell type, promotes the aerobic glycolysis and apoptosis resistance of BC cells by stabilizing HIF-1α, leading to tumor glycolysis and chemoresistance in vivo." (PMID 32503543, 2020). "During cancer progression, numerous tumor-associated genes are upregulated by HIF-1α through its binding to HIF response elements (HREs) under hypoxia." (PMID 32883954, 2020). "The VEGF is involved in tumor growth and metastatic potential, associated with radiation by upregulation of HIF-1α and NF-κB." (PMID 32660072, 2020). "Among HIF1α targeted genes, the largest group is associated with glucose uptake and metabolism as reported in tumor cells/tissues under hypoxia." (PMID 33033473, 2020).